IL6 (interleukin 6)
Diseases named in the same sentence as IL6 in open-access papers (continued):
Sharing a sentence is not in itself a finding about the gene and the disease.
Stroke (continued). "To explore underlying mechanisms, we measured serum levels of Brain-Derived Neurotrophic Factor (BDNF), a key marker of neuroplasticity, and pro-inflammatory cytokines Tumor Necrosis Factor-alpha (TNF-α) and Interleukin-6 (IL-6), which are implicated in post-stroke neural injury and repair." (PMID 40904820, 2025). "Notably, biomarkers like tumor necrosis factor-α (TNF-α), C-reactive protein, and interleukin-6 (IL-6) are robustly linked to higher occurrences of stroke, coronary heart disease, and death from cardiovascular disease." (PMID 40270516, 2025). "Consequently, while IL-6 is mechanistically linked to vascular inflammation and plaque instability, it cannot be isolated as an independent predictor of perioperative stroke, myocardial infarction, or mortality within the current evidence base." (PMID 41440557, 2025). "Therefore, PPARα likely restrains the expression of genes linked to IL6/JAK/STAT3 signaling to prevent rampant neuroinflammation in the subacute stroke phase." (PMID 40362325, 2025). "Furthermore, while cytokines such as interleukin-6 (IL-6) have been linked to stroke severity and outcomes, they are less accessible in routine clinical settings due to higher cost, longer turnaround time, and variability in measurement techniques." (PMID 40606131, 2025). "Among inflammatory markers, only IL-6 showed a significant association with stroke occurrence." (PMID 41362543, 2025). "Additionally, alterations in regulatory T cell (Treg) populations and dysregulated cytokine signatures—particularly elevated interleukin-6 (IL-6) and interleukin-10 (IL-10)—have consistently been linked to increased stroke risk and AF recurrence." (PMID 41156185, 2025). "Overall, CRP and IL-6 levels and consequently the risk of a stroke incrementally increases from the NPD to PD to T2D group, as a result of worsening metabolic and inflammatory profiles, with prediabetes representing an intermediate stage of the inflammatory response." (PMID 41296388, 2025). "Furthermore, IL-6 was found to be a biomarker independently associated with recurrent seizure in patients who had first episode of post-stroke seizure." (PMID 39847089, 2025). "Notably, the pathways responsible for inflammatory signaling, such as TNF-α, Stat5, IL-6, and Jak-stat were decreased in MiD mice compared to MiS stroke mice, suggesting reduced brain inflammation in deficiency of gut microbiota." (PMID 40410847, 2025). "A prospective study of over 1000 stroke patients followed for 12 months found that higher serum IL-6 during initial hospitalization was associated with a significantly higher risk of long-term cognitive decline, defined as a reduction of MoCA score by two or more points." (PMID 39063013, 2024). "Studies have shown that microglia can secrete inflammatory factors such as TNFα and IL-6 and cause damage to the blood-brain barrier in stroke, while certain CNS fibroblasts are involved in the repairing process of damaged tight junctions and management of infarct volume." (PMID 39520909, 2024). "Inflammatory markers, particularly IL-6, have shown strong associations with stroke risk." (PMID 39493062, 2024). "Moreover, older patients who experienced stroke exhibit altered circulating levels of neutrophil-associated cytokines, with significantly elevated IL-6 and IL-8 levels." (PMID 37728582, 2024). "We found that per SD (4.26 pg/mL) increase in IL‐6 concentration was associated with a significantly 19% increased risk of stroke recurrence (aOR, 1.19; 95% CI, 1.09–1.29) and a significantly 22% increased risk of disability (aOR, 1.22; 95% CI, 1.15–1.30) at 90 days." (PMID 37287421, 2023). "A meta-analysis of 11 studies comprising over 27,000 stroke-free participants demonstrated that a 1-standard deviation increment in log-transformed IL-6 was associated with an increased risk of first ischaemic stroke over a decade of follow-up (RR 1.19, 95% CI 1.10–1.28)." (PMID 41541100, 2023).
Stroke (continued). "Although less-widely studied, IL-6 may also have utility as a marker of risk in patients with stroke." (PMID 41541100, 2023). "These hypothesis-generating data suggest that IL-6 may have clinical utility as a more specific inflammatory risk marker for predicting recurrent stroke and vascular events compared with CRP." (PMID 41541100, 2023). "Mediation analyses under the counterfactual framework were performed to examine the potential causal chain in which stroke recurrence may mediate the relationship between IL‐6 and functional outcome." (PMID 37287421, 2023). "Associations of IL‐6 with stroke recurrence and functional disabilities at 90 days." (PMID 37287421, 2023). "High IL-6 levels are independent predictors of stroke or death in patients at high risk of AF." (PMID 38203704, 2023). "Associations between per SD of IL‐6 and 90‐day disability mediated by follow‐up stroke recurrence." (PMID 37287421, 2023). "In this study, our results showed that astrocytic IL-17A promoting post-stroke angiogenesis in enriched animals might be linked with the upregulation of IL-6, JAK2, and STAT3, and moreover, that this promoting effect was neutralized by anti-IL-17 mAb." (PMID 36873773, 2023). "In ischemia caused by stroke increased IL-6 levels could be seen and data showed subsequently aggravated inflammation and histopathologic findings." (PMID 37790622, 2023). "Some data also point to an association of hsCRP and IL-6 with recurrent stroke." (PMID 37762627, 2023). "The subgroup analysis of our study showed that the anti-inflammatory drugs targeting the central IL-6 inflammatory signaling pathway can reduce the incidence of primary outcome (composite outcome of cardiovascular death, MI, or stroke), as well as the risk of MI and coronary revascularization." (PMID 35246052, 2022). "However, bethanechol caused a large increase in IL‐6 expression in the injured striatum and plasma at 24 h after stroke in our mice." (PMID 35531929, 2022). "The higher the expression level of IL-6, the greater the risk of stroke recurrence." (PMID 35419117, 2022). "High CRP and IL-6 concentrations are risk factors for stroke." (PMID 36353279, 2022). "Furthermore, a meta-analysis identified IL-6 in blood plasma associated with poor clinical outcome after stroke, and elevated levels of IL-6, in particular, are considered characteristic of cytokine storms." (PMID 36140216, 2022). "Evidence has shown that the pro-inflammatory cytokine IL-6 increases after stroke, and higher IL-6 concentrations during the acute phase (< 7 days) after onset were associated with poor short-term and long-term outcomes in stroke patients." (PMID 35016629, 2022). "Moreover, a recent study has demonstrated an inverse association with IL-6 and high sensitivity C-reactive protein levels, suggesting a potential anti-inflammatory role for vitamin D in stroke individuals." (PMID 35681147, 2022). "Peripheral IL-6 and IL-10 levels were linked to worsened or improved stroke outcomes, respectively." (PMID 34966269, 2021). "Our results showing that circulating IL-6 might be associated with depressive symptoms at 3 months after stroke are in line with the results of meta-analyses showing that IL-6 is the most consistently elevated cytokine in the blood of patients with MDD3,4." (PMID 33903586, 2021). "Likewise, patients with PolyVD and IL-6 ≥ 2.64 pg/mL (HR 1.290; 95% CI 1.058–1.572; P = 0.01) had the highest risk of recurrent stroke at 1-year follow-up among groups." (PMID 33927687, 2021). "Indeed, IL-6 levels have been prominently discussed as potential biomarkers for ischemic stroke risk, outcome after stroke and even infarct size." (PMID 33420113, 2021). "Compared to non-PolyVD and IL-6<2.64 pg/mL patients, patients had non-PolyVD with IL-6 ≥ 2.64 pg/mL (HR 1.245 95%CI 1.072–1.446; P < 0.001) and PolyVD with IL-6 <2.64 pg/mL (HR 1.251 95%CI 1.002–1.563; P = 0.04) were associated with an increased risk of recurrent stroke during 1-year follow-up." (PMID 33927687, 2021).
Stroke (continued). "Increased circulating levels of IL-6 have been regularly associated with poor-outcome after stroke." (PMID 33578805, 2021). "IL6 encodes the interleukin-6 (IL-6) protein, which is implicated in several diseases involving immune mediated damage of the vascular endothelium and serves as an important biomarker in human stroke." (PMID 33668216, 2021). "We assessed whether NF-L, S100B, and IL-6 were associated with clinical severity on admission (Scandinavian Stroke Scale, SSS), diagnosis of ischemic stroke vs. TIA, and functional outcome at 3 months (modified Rankin Scale, mRS)." (PMID 32595585, 2020). "In a logistic regression analysis adjusted for age, stroke severity, pneumonia, leukocyte count, plasma interleukin-6, and TNFα release ex vivo, a higher GC sensitivity index was associated with a higher risk of poor outcome after stroke (OR 2.32, 95% CI 1.21–4.45, P = 0.01)." (PMID 32107751, 2020). "Some of these are linked to stroke risk and have already been (e.g., renal failure, IL-6, vWF)." (PMID 32154260, 2020). "In spite of these limitations, the two promising candidates for future investigations are SAP as a potentially modifiable post-stroke complication, and IL-6 as blood-based biomarker, both of which were associated with shorter survival in our patient population." (PMID 31269910, 2019). "Novel associations suggest that modulating the action of IL6 could reduce the risk of AF and stroke." (PMID 31552141, 2019). "Several studies also demonstrate that neurotoxicity induced by inflammation and stroke is associated with elevation of interleukin-6 (IL-6) including one study showing that IL-6 correlates significantly with the outcome and mortality rate of ischemic stroke patients." (PMID 30915140, 2019). "We hypothesized that elevated serum levels of IL6 and LpPLA2 are independently associated with worse functional trajectories in those free of stroke at baseline, and there are several unique approaches of this analysis." (PMID 30934019, 2019). "However, it is worth pointing out that our analyses revealed causal inference for IL6 signaling with any stroke." (PMID 31552141, 2019). "Therefore, interventional studies aiming to block microglia/macrophages M1 polarization, or directly target IL-6 and IL-1β, will be needed to evaluate if a causal link exists between inflammation and stroke severity in CKD." (PMID 31015533, 2019). "Moreover, polymorphisms of the promoter IL‐6 gene have been proved to be associated with the presence of stroke while polymorphisms of the TNF gene and IL‐1 gene have been suspected to be associated with ischemic stroke." (PMID 29484258, 2018). "IL-6 levels are closely associated with stroke severity, infarct volume, and poor prognosis." (PMID 30245755, 2018). "Importantly, both TNF-α and IL-6 are strongly implicated in the vascular permeability in rodents subjected to stroke." (PMID 29452577, 2018). "In conclusion, our results demonstrated that the associations between serum vitamin D and IL‐6 levels in stroke patients, suggesting a potential anti‐inflammatory role for vitamin D. It indeed provides evidences for the pathophysiology of PSD caused by vitamin D deficiency." (PMID 29484258, 2018). "Increased levels of IL6 in blood have been linked to worse outcome after stroke, but the authors conclude, as we do, that the clinical usefulness may be small, since this again may be a question of cutoff levels." (PMID 30367354, 2018). "Notably, IL-6 has been reported to function as a main stimulator of CRP that predicts clinical stroke risk." (PMID 29403373, 2017). "However, the NIHSS at stroke onset showed an independent positive association only with IL-6 and IL-10 on day 3 (all p < 0.05)." (PMID 27682880, 2017). "Moreover, a higher level of serum IL-6 is also associated with an increased risk of recurrent vascular events after stroke." (PMID 27146847, 2016).
Stroke (continued). "More specifically IL-1, IL-6, IL-10, IL-17, IL-23, TNFα, transforming growth factor β (TGFβ) and IFNγ are seen to increase after stroke, IL-17, IL-23 and IFNγ being associated with exacerbation of stroke in mice, whereas IL-10 and TGFβ are protective." (PMID 25705177, 2015). "Finally, the RE-LY biomarker study showed an independent association between IL-6 and stroke or systemic embolism, while CRP levels were associated with cardiovascular mortality after multivariate adjustments." (PMID 25215263, 2014). "Finally, it is hard to escape the obvious conclusion from the present study that plasma level of IL-6 is of value in determining the extent of ischemic stroke and associated with mid-term outcome and mortality rate of the stroke patients." (PMID 25295149, 2014). "The most extensively studied cytokines associated with stroke are IL-1β, IL-10, IL-6 and TNF-α." (PMID 23514014, 2013). "Animal models showed less association between IL-6 and stroke." (PMID 23431245, 2013). "The increased production of IL-6 in patients with large strokes could be the result and/or the cause of the enlarged cerebral infarctions." (PMID 22533966, 2012). "Multivariate logistic regression analysis established a level of significance of IL-6 contents toward the mean predicted probability of ischemic lesion size at the twenty-fourth hour from stroke onset, after all the acute phase factors and risk factors that we examined were entered into the model." (PMID 21450100, 2011). "This may further exacerbate stroke evolution in elderly patients, and this association of IL-6 with senescence requires further investigation." (PMID 22132330, 2011). "In these individuals, who were randomised to placebo or treatment with pravastatin, IL-6, CRP, and fibrinogen all predicted cardiovascular death, and IL-6 in particular added significantly to conventional risk factors in predicting those suffering fatal myocardial infarction or fatal stroke." (PMID 19901972, 2009). "In this large cohort of stroke patients, blood markers of the acute inflammatory response were associated with poor outcome after stroke, though only IL-6 showed independent association after adjustment for confounding factors, including levels of other markers." (PMID 19901973, 2009). "However, it did identify two polymorphisms that appear to influence stroke risk via a gene-environment interaction with cigarette smoking, IL6 rs2069830 and CD-14 rs2569190." (PMID 18727828, 2008). "Our results, consistent with other studies, demonstrates that genetic variation in IL-6 may modify stroke risk, and that this increased risk may be due to synergistic effects between proinflammatory genotypes and smoking." (PMID 18727828, 2008). "This study demonstrates that inflammatory gene SNPs are associated with early-onset ischemic stroke among African-American women (IL6) and that cigarette smoking may modulate stroke risk through a gene-environment interaction (IL6 and CD14)." (PMID 18727828, 2008). "This study demonstrates that inflammatory gene SNPs may be associated with early-onset ischemic stroke among African-American women (IL6) and that cigarette smoking may modulate stroke risk through a gene-environment interaction (IL6 and CD14)." (PMID 18727828, 2008). "Only IL6 (rs2069832) was found to be associated with stroke, and only among African-Americans." (PMID 18727828, 2008). "In addition, SHBG could markedly suppress lipopolysaccharide-induced inflammatory biomarkers in macrophages and adipocytes, such as monocyte chemoattractant protein-1, TNFα, and IL-6, which have been reported to be closely related to stroke risk and prognosis." (PMID 40728963, 2025). "Emerging evidence suggests that higher circulating levels of IL-6 are significantly associated with an elevated risk of AF recurrence following cardioversion and after radiofrequency catheter ablation, with poorer long-term outcomes, including greater risk of stroke and all-cause mortality." (PMID 40868104, 2025).
Stroke (continued). "By combining these markers with others that evaluate different pathophysiological pathways associated with stroke such as IL-6 and D-dimer, we can develop a comprehensive panel of blood biomarkers that may provide a more accurate clinical prognosis for stroke patients with prediabetes and T2DM." (PMID 41150802, 2025). "Only half of the excess stroke risk among blacks in the United States is attributable to traditional risk factors—the pro-inflammatory marker interleukin-6 (IL-6) and the highly genetically-determined lipoprotein [a] (Lp(a)) are higher in some ethnicities and may elevate stroke risk." (PMID 38921680, 2024). "Importantly, the microglia in GFAP-IL6 mice had a similar morphology to microglia in the brains of patients with NMOSD and animals with pathologies associated with elevated IL-6, such as acute LPS-induced endotoxemia, stroke and ischemic stroke and reperfusion." (PMID 35429976, 2022). "However, whether combined PolyVD and elevated IL-6 levels would increase the risk of poor outcomes of stroke patients is yet unclear." (PMID 33927687, 2021). "Circulating IL-6 might be associated with depressive symptoms occurring at 3 months after stroke." (PMID 33903586, 2021). "Thus, combined PolyVD and elevated IL-6 levels could increase the stroke risk stratification efficiency compared with when used alone." (PMID 33927687, 2021). "IL-6 is a pro-inflammatory cytokine that is involved in acute systemic inflammatory responses as well as delayed responses through activation of T and B cells that is of specific interest to this study since it has been associated with worse short-term stroke outcomes." (PMID 35126360, 2021). "Although both PolyVD and IL-6 are considered risk factors for poor outcomes of ischemic stroke, there were limited data on their combined effect which might raise the risk stratification in stroke patients." (PMID 33927687, 2021). "Additionally, the recurrence of stroke was also associated with higher levels of IL-6." (PMID 33049931, 2020). "There are reports that TNF-α and IL-6 may increase the risk of stroke." (PMID 33187206, 2020). "Moreover, albuminuria may be a marker for the acute phase reaction under stroke-related systemic inflammation and has been correlated with interleukin-6 level, which is associated with stroke lesion severity and worse outcomes." (PMID 27213281, 2016). "Furthermore, exploring the cellular mechanism underlying IL-6, IL-10 and HLA-DR release after stroke could pave the way towards preventing SAI." (PMID 27409177, 2016). "We therefore aimed to validate the suggestion that several markers of the acute phase response—CRP, IL-6, white cell count, fibrinogen, or glucose—are reliably associated with poor outcome after ischemic and hemorrhagic stroke in a large prospective cohort of stroke patients." (PMID 19901973, 2009). "Furthermore, several studies have demonstrated that IL-6 polymorphisms may mediate carotid artery intima-media wall thickness, an intermediate marker of stroke risk." (PMID 18727828, 2008). "Recent studies have shown a link between PM exposure and oxidative stress, which may impair endothelial-dependent vasodilation as well as increased levels of fibrinogen (an established risk factor for myocardial infarction and stroke), C reactive protein, IL-6, and IL-8." (PMID 17450221, 2007). "TNF-α and IL-6 both exhibited a rapid exponential rise in concentration within the first 6 hours following simulated stroke onset, with their peaks occurring within the early inflammatory window (6–24 hours)." (PMID 41557608, 2026). "In stroke survivors, sustained muscle wasting can be a consequence of chronic IL-6 elevation, which promotes a catabolic state and can also lead to a shift in muscle fiber types from slow-twitch (type I) fibers to fast-twitch (type II) fibers." (PMID 41598337, 2026).